CTSC (cathepsin C)
Diseases named in the same sentence as CTSC in open-access papers (continued):
Sharing a sentence is not in itself a finding about the gene and the disease.
epithelial ovarian cancer (2 papers, 2010 to 2018). "CTSC appears to regulate the degradation of extracellular matrix components that is associated with the metastasis of oral and ovarian cancer cells." (PMID 29552294, 2018). "Our results suggest that CTSB, CTSC, and CTSS have important functions in the development of epithelial ovarian cancer." (PMID 20727192, 2010). "The results of the present study demonstrate that CTSB, CTSC, and CTSS are upregulated in cancerous ovaries of chickens, suggesting that CTSB, CTSC, and CTSS have potentially important functions in the development of ovarian cancer in chickens." (PMID 20727192, 2010).
influenza (2 papers, 2017 to 2022). An acute viral infection of the respiratory tract, occurring in isolated cases, in epidemics, or in pandemics; it is caused by serologically different strains of viruses (influenzaviruses) designated A, B, and C, has a 3-day incubation period, and usually lasts for 3 to 10 days. "Notably, a number of proteins lacking a signal peptide and not annotated as ‘secreted’ elsewhere were overrepresented in the influenza stimulated group, including the proteases cathepsin c, cathepsin z, legumain, and the transcription factor IRF8." (PMID 35401570, 2022). "We also identified two novel host factors, CTSC and TMPRSS9, which have not previously been reported to be associated with influenza replication and represent opportunities for future study." (PMID 28272419, 2017).
oral cancer (2 papers, 2020 to 2023). "Further, higher expression of CTSC, HIF1A, and IL1B was observed in both stages of oral cancer." (PMID 38234400, 2023).
osteoarthritis (2 papers, 2011 to 2012). A noninflammatory degenerative joint disease occurring chiefly in older persons, characterized by degeneration of the articular cartilage, hypertrophy of bone at the margins and changes in the synovial membrane. "Moreover, the expression of several key features of osteoarthritis pathology and pro-inflammatory mediators (e.g. cysteine proteases cathepsin S and cathepsin C), were detected among the highly regulated genes during DN-Erg chondrocyte culture." (PMID 23155398, 2012).
Palmoplantar hyperkeratosis (2 papers, 2021 to 2022). Abnormal thickening of the skin localized to the palm of the hand and the sole of the foot. "Atypical phenotypes of CTSC mutations with palmoplantar hyperkeratosis but lack of periodontal involvement and vice versa have been described." (PMID 36554029, 2022).
coinfection (1 paper, 2024). The simultaneous infection of a host by multiple pathogen species. "We conclude that the observed increase in cathepsin C enzymatic activity during coculture assays in Mtb–HIV coinfection is a result of the activation of this enzyme from cytotoxic lymphocytes following the depletion of CstF from Mtb-infected Mφs." (PMID 39125711, 2024).
congenital disorder of glycosylation (1 paper, 2023). Congenital disorder of glycosylation (CDG) is a fast growing group of inborn errors of metabolism characterized by defective activity of enzymes that participate in glycosylation (modification of proteins and other macromolecules by adding and processing of oligosaccharide side chains). "The tetrameric form of cathepsin C (CTSC) was expressed at low levels in both cases with congenital disorder of glycosylation (CDG)." (PMID 37069668, 2023).
cyst (1 paper, 2024). A sac-like closed membranous structure that may be empty or contain fluid or amorphous material. "Moreover, other elevated factors in our data set are known to regulate immune cell activity and infiltration (e.g., GDIB, CTSC), which are also known to exacerbate and promote cyst growth." (PMID 38385746, 2024).
cystic fibrosis (1 paper, 2012). Autosomal recessive disorder caused by pathogenic variants in the CFTR gene (cystic fibrosis transmembrane conductance regulator), which encodes a chloride and bicarbonate channel expressed in epithelial cells, and follow the diagnosis criteria. "Both SERPINB4 and CTSC are up-regulated in IL13 treated human primary bronchial epithelial cells on air liquid interface culture, and PLA2G4A is more active in bronchial explants from individuals with cystic fibrosis." (PMID 22676183, 2012).
dental caries (1 paper, 2022). The decay of a tooth, in which it becomes softened, discolored, and/or porous. "Interestingly, several identified CTSC mutations were previously found to be associated with severe dental caries and periodontitis; this might explain the correlation between dental caries and periodontal diseases." (PMID 35782115, 2022).
diabetic cardiomyopathy (1 paper, 2021). Diabetic cardiomyopathy is a disorder of the heart muscle in people with diabetes. "Of note, NSPs are involved in the progression of diabetic cardiomyopathy, since genetic knockout of dipeptidyl peptidase I (DPPI, also known as cathepsin C), which is an essential protease for maturation of NSPs, prevents myocyte apoptosis and fibrosis development." (PMID 34869231, 2021).
esophageal cancer (1 paper, 2024). A primary or metastatic malignant neoplasm involving the esophagus. "Among them, the genes CTSZ, CTSC, DAD, COLEC12, ATOX1, etc., in the TUBA1B+Mac-C0 cluster have a causal relationship with esophageal cancer." (PMID 38434988, 2024). "Genes causally associated with the occurrence of esophageal cancer are identified within the AGG cluster, including CTSZ, CTSC, DAD, COLEC12, ATOX1, etc., offering new evidence for clinical immune therapy." (PMID 38434988, 2024). "Mendelian randomization analysis revealed a causal relationship between genes such as CTSZ, CTSC, DAD, COLEC12, ATOX1, within the AGG cluster, and the onset of esophageal cancer." (PMID 38434988, 2024). "The Mendelian randomization results indicate a causal relationship between genes such as CTSZ, CTSC, DAD1, COLEC12, ATOX1 in the TUBA1B+Mac-C0 cluster and the occurrence of esophageal cancer." (PMID 38434988, 2024).
gastric cancer (1 paper, 2023). A primary or metastatic malignant neoplasm involving the stomach. "Indeed, decreased levels of CTSC reduced gastric cancer cell growth and induced cell cycle arrest, thereby inhibiting cancer progression." (PMID 36831614, 2023).
Hyperglycemia (1 paper, 2025). An increased concentration of glucose in the blood. "Cathepsin C overexpression in podocytes causes cytoskeletal disruption and insulin resistance under hyperglycemia." (PMID 41009556, 2025).
Hypertension (1 paper, 2025). The presence of chronic increased pressure in the systemic arterial system. "Clinically, SCFA levels were inversely correlated with cathepsin C expression, which was associated with hypertension and proteinuria." (PMID 41333475, 2025). "Interventional studies in animals confirmed that SCFA administration downregulated placental cathepsin C, concurrently alleviating hypertension and placental damage." (PMID 41333475, 2025). "In rats, SCFA supplementation significantly reduced cathepsin C levels and alleviated PE symptoms, including hypertension, proteinuria, and fetal growth restriction." (PMID 41333475, 2025). "In contrast, forced overexpression of cathepsin C completely negated the protective benefits of SCFA supplementation, reverting hypertension and proteinuria to pathological levels." (PMID 41333475, 2025).
keloid (1 paper, 2025). An irregularly shaped, elevated mark on the skin caused by deposits of excessive amounts of collagen during wound healing. "This “dual‐locked” design strategy guarantees the specific activation of FC‐1 in the presence of both FAPα and CTSC, thereby enabling precise differentiation between cSCC tissues and keloid tissues." (PMID 41035512, 2025).
leukaemia (1 paper, 2014). "This is in keeping with results of a study using a leukaemia cell line which indicated that cathepsin C is not the sole enzyme involved in post-translational processing of PR3." (PMID 25260376, 2014).
lymph node metastasis (1 paper, 2018). "Higher tumor tissue expressions of two proteins, AGRN and CTSC, were found to be significantly associated with lymph node metastasis, distant metastasis at diagnosis, and poor prognosis of PTC patients." (PMID 29552294, 2018). "Higher expression levels of AGRN and CTSC were found to be significantly correlated with lymph node metastasis, distant metastasis at diagnosis, tumor multicentricity, TNM stage, and disease-specific mortality." (PMID 29552294, 2018).
malaria (1 paper, 2014). Malaria is a serious and sometimes fatal disease caused by a parasite that commonly infects a certain type of mosquito which feeds on humans. "In this report, we describe the systematic substrate specificity analysis of three cathepsin C orthologs from Homo sapiens (human), Bos taurus (bovine) and Plasmodium falciparum (malaria parasite)." (PMID 24381006, 2014).
mastitis (1 paper, 2021). Inflammation of breast tissue during lactation or postpartum due to an obstructed duct or infection. "Through bioinformatics investigation, IL8, IL10, IL18, and CTSC were recognized as the essential biomarkers for E. coli mastitis and were related to the immune response of bovine mastitis." (PMID 34637035, 2021).
melanoma (1 paper, 2025). A malignant, usually aggressive tumor composed of atypical, neoplastic melanocytes. "The results indeed revealed approximately a twofold lower expression of cathepsin C in malignant melanoma compared to normal skin." (PMID 41155949, 2025). "Considering that LLOMe-induced LMP requires cathepsin C, whereas mefloquine and siramesine act independently of this protease, we hypothesized that the limited sensitivity of melanoma cells to LLOMe might be due to reduced cathepsin C expression." (PMID 41155949, 2025).
neuroblastoma (1 paper, 2023). Neuroblastoma (NB) is the most common solid, extracranial childhood tumor. "The microglial cells contained robust levels of cathepsinsB, D, and X, along with cathepsins A, K, L, and C. In the SH-SY5Yneuroblastoma cells, only two cathepsins, B and D, were detected;in the SKNMC neuroblastoma cells, cathepsins B and D were abundantand low levels of cathepsin C were detected." (PMID 37459182, 2023).
neuronal ceroid lipofuscinosis (1 paper, 2023). "Genes for lysosomal proteases are increased, including CTSB, CTSC and CTSD, which is mutated in neuronal ceroid lipofuscinosis (NCL) type 10." (PMID 37747131, 2023).
nodular sclerosis (1 paper, 2022). "In our study, genes related to major histocompatibility complex (MHC) class I and II machinery/biosynthesis such as HLA-DRA, CTSS, HLA-DPA1, HLA-DPB1, CTSC, B2M genes were expressed at higher levels in the mixed-cellularity subtype than in nodular sclerosis subtype at diagnosis." (PMID 36230815, 2022).
Obesity (1 paper, 2022). Accumulation of substantial excess body fat.
Palmoplantar keratoderma (1 paper, 2025). Abnormal thickening of the skin of the palms of the hands and the soles of the feet. "Herein, we report a 6-year-old girl presenting with palmoplantar keratoderma, recurrent skin infections, necrotizing granulomatous inflammation, and delayed growth, who was genetically verified to have a CTSC mutation linked to PLS, despite the absence of oral manifestations." (PMID 41133531, 2025).
pancreatic squamous cell carcinoma (1 paper, 2025). "Previous studies reported increased CTSC expression in myeloid cells from normal pancreas to pancreatic squamous cell carcinoma and its key role in islet carcinogenesis." (PMID 41346619, 2025).
pneumonia (1 paper, 2023). An acute, acute and chronic, or chronic inflammation focally or diffusely affecting the lung parenchyma, caused by an infection in one or both of the lungs (by bacteria, viruses, fungi, or mycoplasma.). "Cathepsin C (CTSC) is a serine protease released by neutrophils that can result in increased tissue-degradation, being implicated in the pathophysiology of pneumonia and ARDS in mechanically ventilated adults." (PMID 37474963, 2023).
renal cell carcinoma (1 paper, 2021). "Moreover, TSAIII demonstrates significant antimetastatic activity against renal cell carcinoma cells through the inhibition of cathepsin C expression at the AKT/miR-129-5p axis." (PMID 33799345, 2021).
tumor (73 papers, 2010 to 2026). "Activated cytotoxic T cells infiltrate into the tumor area and kill tumor cells by enhancing pore formation in the tumor cell membrane and causing subsequent secretion of death-inducing granules containing granzymes, perforin, cathepsin C, and granulysin." (PMID 37759777, 2023). "Collectively, these data demonstrate that CTSC promotes NETosis in tumor, impairs chemotherapy efficacy, and predicts poor patient outcomes." (PMID 41480760, 2026). "Mechanistically, macrophage-engulfed cathepsin C (CTSC) from tumor debris activates TLR4/NF-κB signaling, upregulating CXCL1/2 and complement factor B (CFB) to drive neutrophil recruitment and NET formation." (PMID 41480760, 2026). "Based on the TCGA database, we observed that CTSC expression was also significantly elevated in ESCC tumor samples." (PMID 40740774, 2025). "The results showed that knockdown of CTSC inhibited tumor growth in vivo and reduced the protein of the fibroblast marker α-SMA." (PMID 40740774, 2025). "For instance, tumor-secreted cathepsin C (CTSC) activates neutrophil protease 3 (PR3), triggering the CTSC-PR3-IL-1β axis." (PMID 41459159, 2025). "The results revealed that CTSC was significantly highly expressed in the epithelial cells of tumor samples (P<0.001)." (PMID 40740774, 2025). "Recent studies reveal that tumor‐secreted cathepsin C (CTSC) facilitates pulmonary tumor colonization by recruiting neutrophils and inducing neutrophil extracellular trap (NET) formation." (PMID 40470380, 2025). "Within the tumor microenvironment, cathepsin C activates membrane-bound PR3 on neutrophils, facilitating the processing of IL-1β and NF-κB activation." (PMID 41303697, 2025). "In vitro experiments showed that knockdown of CTSC inhibited tumor growth and expression of fibroblast markers." (PMID 40740774, 2025). "For instance, Cathepsin Z (CTSZ) and Cathepsin C (CTSC), members of the tissue proteinase family, regulate the adhesion and migration of immune cells and tumor cells." (PMID 38434988, 2024). "IHC and western blotting further confirmed the higher expression of CTSC in HCC tissues compared to the adjacent tumor tissues." (PMID 38742112, 2024). "Other implicated mechanisms are NET-DNA receptors on the tumor cell membrane; cathepsin C, a protease released by tumor cells that primes NET formation, and the release of G-CSF at sites of NET dissemination and interleukin disbalance." (PMID 38612841, 2024). "During mammary carcinogenesis, cathepsin C expression and enzymatic activity is elevated, mainly in stromal cells like leukocytes and fibroblasts, but in tumor cells as well." (PMID 36002710, 2023). "Mechanically, tumor-secreted cathepsin C promoted the maturation and release of IL-1β in pulmonary neutrophils by activating the neutrophils membrane localization proteinase 3 (PR3) through enzyme digestion." (PMID 35719975, 2022). "While in vivo studies, Decursin decreased the growth of tumor spheroids and patient-derived gastric organoids, and regulated the expression of CTSC and autophagy-related proteins, which in turn validated the in vivo experimental results." (PMID 36091754, 2022). "As we know, active CD8+ T cells bind and kill tumor cells by secreting granzymes, perforin, and cathepsin C." (PMID 36212126, 2022). "In human and mouse breast cancer, recent studies reported the role of tumor cell-secreted protease cathepsin C-mediated signaling in neutrophil recruitment and NET formation." (PMID 35574410, 2022). "Cathepsin C, for example, has been demonstrated to recruit neutrophils to the primary tumor and induce NETs that enhance tumor cell dissemination." (PMID 34830776, 2021).